PSMA1 (proteasome 20S subunit alpha 1)
Diseases named in the same sentence as PSMA1 in open-access papers (continued):
Sharing a sentence is not in itself a finding about the gene and the disease.
tumor (continued). "Further, in vivo antitumor activity studies of PSMA-1-VcMMAE-Cy5.5 showed that it effectively inhibited PC3pip tumor growth and prolonged animal survival in a dose dependent manner without loss of body weight)." (PMID 33499427, 2021). "Further antitumor activity studies using mice bearing heterotopic PC3pip tumors showed that PSMA-1-VcMMAE effectively inhibited tumor growth at the dose of 382 nmol/kg compared to MMAE at 700 nmol/kg and PSMA-ADC at 50 nmol/kg." (PMID 33499427, 2021). "It was found that treatment of mice that had extremely large tumors (≈2000 mm3) with PSMA-1-VcMMAE-Cy5.5 was able to ablate the tumor." (PMID 33499427, 2021). "Delivery of Pc158 via PSMA-targeted gold nanoparticles improved tumor accumulation of Pc158 via several mechanisms, resulting in significant tumor growth inhibition as compared to small molecule delivery, i.e., PSMA-1-Pc413." (PMID 34203805, 2021). "In the present study, we investigated the mRNA expression differences between tumor and normal tissues in multiple cancers for PSMA1-7 using Oncomine and TCGA databases." (PMID 27966459, 2017). "When grouped by tumor stage, all seven PSMAs showed different prognostic values in stage 1, whereas only PSMA1, PSMA2 and PSMA5 were correlated with OS or PPS in stage 2." (PMID 27966459, 2017). "PSMA1 plays a role in gating the entry of proteins into the proteasome and its overexpression has been involved in tumor genesis." (PMID 26390031, 2015). "Mice treated with either RT or the inducible PSMA1 knockdown in tumor cells also showed progressive tumor growth and poor survival." (PMID 24040035, 2013). "Significantly increased IR-induced γ-H2AX foci in tumor specimens persisted at 1, 6, and 24 hours with PSMA1 knockdown compared to control, indicating delayed DNA DSB repair." (PMID 24040035, 2013). "IR-induced FANCD2 focus formation was also reduced in tumor specimens showing inducible PSMA1 knockdown." (PMID 24040035, 2013). "After RT treatments, PSMA1 knockdown was discontinued, and mice were followed for up to 100 days after tumor formation." (PMID 24040035, 2013). "However, PSMA-1-MMAE-IR700 demonstrated peak tumor accumulation 1 h post-injection followed by a subsequent active clearance." (PMID 39000194, 2024). "All these results suggest that PSMA1 acts as a tumor indicator in GC and may be a valuable prognostic biomarker in GC patients." (PMID 36424389, 2022). "PSMA-1-MMAE-IR700 fluorescence signal was highly co-localized to GFP signal from the tumor." (PMID 35265213, 2022). "Therefore, PSMA-1-MMAE-IR700 can help surgeons visualize the tumor and resect tumors during surgery." (PMID 35265213, 2022). "In conclusion, we demonstrated that PSMA1 promotes tumor growth on GC in vivo." (PMID 36424389, 2022). "At the dose of 1910 nmol/kg, PSMA-1-VcMMAE showed the ability to successfully inhibit C4-2 tumor growth with no weight loss and prolonged animal survival significantly (p = 0.0018) with a 40% cure rate." (PMID 33499427, 2021). "It was also found that PSMA-1-VcMMAE was significantly more effective at inhibiting PSMA-positive PC3pip tumor growth than PSMA-negative PC3flu tumor growth when used at the dose of 955 nmol/kg (p = 0.0493), indicating selective killing of PSMA-1-VcMMAE by targeting PSMA." (PMID 33499427, 2021). "However, only PSMA1 and PSMA3 were significantly associated with poor outcomes in patients with tumor grade II." (PMID 27966459, 2017). "Notably, PSMA-1-VcMMAE showed the ability to significantly prolong the survival time of animals not only in heterotopic and orthotopic PC3pip tumors, but also in the metastatic PC3pip tumor model." (PMID 33499427, 2021). "In contrast, PSMA-1-MMAE-Pc413 had a peak accumulation time at 24 h post-injection and was cleared relatively slowly from the tumor." (PMID 39000194, 2024).
tumor (continued). "We analyzed PSMA1 and TAZ expression in tumor samples and adjacent normal tissues from 94 GC patients using tumor microarrays (TMA), along with their corresponding clinicopathologic information." (PMID 36424389, 2022). "KTN1 knockdown increases the expression of CCDC40, PSMA1, and ADRM1 to mediate tumor suppressor functions in vivo and in vitro." (PMID 34689164, 2021). "Results showed that gene signatures such as PSMA1, FGFR3, C7orf46, RNF7, and ZNF35 were differentially expressed in normal and tumor samples with the P-value < 0.05." (PMID 32528533, 2020). "Through a combination of bioinformatics analysis and experiments, we demonstrated that neutrophils regulate the tumor microenvironment via the PSMA1-NF-κB-HIF-1α signaling axis, promoting the malignant progression of tumor cells and thus strongly supporting tumor growth." (PMID 40901472, 2025). "Similarly, YC-273-IRDye800CW, PSMA-1-IRDye800CW, PSMA-1-Cy5.5, and SCE-IRDye800CW have been established and preliminarily validated in PSMA+ PCa tumor-bearing mice 92-94." (PMID 38773975, 2024). "PSMA-1-MMAE-Pc413 without PDT significantly inhibited tumor growth rate (p = 0.0058 vs. PBS) and extended survival times (p = 0.0079 vs. PBS), showing that MMAE itself is a potent cytotoxic agent." (PMID 39000194, 2024). "Both PSMA1 and TAZ showed high expression in most tumor specimens." (PMID 36424389, 2022). "In this study, PSMA-1-MMAE-IR700 showed the ability to accumulate in tumor metastases in lymph nodes, which indicates that the drug may be effective in combating tumor metastases." (PMID 35265213, 2022). "PSMA-1-MMAE-IR700 without light significantly inhibited tumor growth and prolonged animal survival, indicating that targeted delivery of MMAE improved antitumor activity." (PMID 35265213, 2022). "During PSMA-1-MMAE-IR700 + PDT treatment, initial tumor swelling was observed in some mice, resulting in slightly larger initial tumor sizes than those measured after treatment with PSMA-1-MMAE-IR700 without PDT." (PMID 35265213, 2022). "In contrast, the small molecule PSMA-1-Pc413 showed good accumulation in the tumor at 24 h, but no Pc413 fluorescence recovery was observed after one light PDT irradiation." (PMID 34203805, 2021). "Our study also revealed that reduced PSMA1 levels lead to decreased expression of NET markers in HL60 cells, suggesting that inhibiting PSMA1 may suppress NET formation and improve the immunosuppressive properties of the tumor microenvironment." (PMID 40901472, 2025). "Within tumor tissue in the adequate iron group, and more so in tumors from the excess iron diet group, we found there was also significantly greater (p ≤ 0.05) expression of proteins involved in protein degradation (ANPEP, DPP7, ITGB1, PSMA1, PSMA2, PSMA3, and SERPINB1)." (PMID 38732562, 2024). "None of the mice in PSMA-1-Pc413 + PDT and PSMA-1-MMAE-Pc413 with no PDT treatment groups was tumor-free and all mice in these groups died before the 90-day experimental time, indicating PDT or chemotherapy treatment alone is not effective in eradicating the tumors." (PMID 39000194, 2024).
infection (4 papers, 2017 to 2020). The state of being infected such as from the introduction of a foreign agent such as serum, vaccine, antigenic substance or organism. "Our study found a set of proteasome-encoding genes that included PSMA1, PSMD10, PSMD14 and PSMA4, that were all down-regulated during the early phase of infection." (PMID 30789917, 2019).
neurological disease (1 paper, 2016). "Some downregulated proteins such as DPYSL2, TPI1, ALDH, and UCHL1 were found to play critical roles in the neurological disease and PSMA1, PSMA3, PSMC2, PSMD11, and UCHL1 in protein homeostasis." (PMID 27857231, 2016).
PSMA1 also shares sentences with these, for which no sentence is quoted: depression (2 papers); pancreatic cancer (2); Parkinson disease (2); amyotrophic lateral sclerosis (1); Anxiety (1); Autoimmunity (1); bladder cancer (1); cervical cancer (1); connective tissue disease (1); endotoxemia (1); Epstein-Barr virus infection (1); esophageal squamous cell carcinoma (1); glioblastoma multiforme (1); glioma (1); Hypertension (1); invasive carcinoma (1); kidney renal cancer (1); liver cancer (1); Lung Squamous Cell Carcinoma (1); myasthenia gravis (1); Nail dysplasia (1); neurodevelopmental disorder (1); neuroendocrine pulmonary tumor (1); neuroendocrine tumors (1); prion disease (1); systemic lupus erythematosus (1); varicocele (1).